GAB2 (GRB2 associated binding protein 2)
Diseases named in the same sentence as GAB2 in open-access papers (continued):
Sharing a sentence is not in itself a finding about the gene and the disease.
Obesity (3 papers, 2021 to 2024). Accumulation of substantial excess body fat. "Variations in the gamma-aminobutyric acid receptor subunit alpha-2 (GABRA2) and GRB2-associated binding protein 2 (GAB2) genes are linked to behavioural problems, substance use, drinking behaviour, and obesity." (PMID 38674857, 2024). "All the results above indicated that Gab2 deficiency can diminish the development of obesity by affecting the number, size, and function of adipocytes." (PMID 33637697, 2021). "The study reveals novel regulation of Gab2 on lipid homeostasis and adipocytes function, as well as provides a novel target for the treatment of obesity and associated complications." (PMID 33637697, 2021). "However, Gab2 was found to be recruited by a variety of pathogenic factors to initiate the pathogenesis of hepatitis, fatty liver, and obesity by mediating a variety of signaling molecules, thus promoting the occurrence and development of liver cancer." (PMID 36421826, 2022). "Our research suggests that deletion of Gab2 suppresses diet-induced obesity by multiple pathways and Gab2 may be a novel therapeutic target for the treatment of obesity and associated complications." (PMID 33637697, 2021). "Our current research exhibits the regulation of Gab2 on adipose tissue inflammation and brown adipose tissue function, which expands and emphasizes the therapeutic role of Gab2 and provides a novel target for the treatment of obesity and associated complications." (PMID 33637697, 2021). "Deletion of the Gab2 gene and the suppression of Gab2 expression ameliorates the pathogenesis of hepatitis, fatty liver, and obesity and suppresses the development of liver cancer." (PMID 36421826, 2022). "This study investigated the effect of signaling scaffolding protein Gab2 on obesity and its relevant regulation mechanism." (PMID 33637697, 2021). "Gab2 is recruited by HFD to promote the development of obesity by regulating multiple pathways and the deletion of Gab2 resists HFD-induced obesity." (PMID 33637697, 2021). "Our results suggested that Gab2 has the potential to regulate glucose homeostasis in obesity." (PMID 33637697, 2021). "In summary, the PI3K/Akt pathway may be a key pathway in the regulation of Gab2 on lipid and glucose metabolism, inflammation, and the differentiation and function of adipose tissue in obesity." (PMID 33637697, 2021). "Here, the deletion of Gab2 may improve obesity by reducing recruitment of macrophages and secretion of inflammatory factors." (PMID 33637697, 2021). "Our observation demonstrated that Gab2 is a key regulator of obesity and suppression of Gab2 may improve the treatment of obesity." (PMID 33637697, 2021).
renal cell carcinoma (3 papers, 2017 to 2022). "The expression and biological function of Grb2-associated binding 2 (Gab2) in renal cell carcinoma (RCC) cells was tested here." (PMID 28412750, 2017).
serous ovarian cancers (3 papers, 2016 to 2022). "We previously found that the scaffold adapter GRB2-associated binding protein 2 (GAB2) is amplified and overexpressed in a subset of primary high-grade serous ovarian cancers and cell lines." (PMID 26657155, 2016). "Moreover, Gab2 is selected by FRMT as the second discriminative protein in OV dataset, and this is in concordance with recent studies that reported Gab2 amplification and overexpression in a subset of primary high-grade serous ovarian cancers and cell lines." (PMID 28934234, 2017).
Bladder cancer (2 papers, 2021 to 2022). "It is interesting to notice that both somatically mutated PRKAR2B and germline-mutated GAB2 were present in a single bladder cancer case (BioSample accession number: SAMN02351138)." (PMID 35033028, 2022).
diabetes (2 papers, 2021 to 2023). "Four genes including GAB2, LMNB2, XAB2 and RBM39 are involved in the regulation of diabetes, fat and insulin signaling, according to text mining." (PMID 34084770, 2021).
epilepsies (2 papers, 2018 to 2024). "The GAB2 insertion is near the adjacent gene NARS2, which has often been associated with epilepsies in human infants and children." (PMID 39596674, 2024).
Hepatitis (2 papers, 2017 to 2022). Inflammation of the liver. "Our previous study identified a signal integration protein, Gab2, that is specifically and highly expressed in fatty liver, hepatitis, liver cancer, and other pathologies and integrates a variety of signaling pathways to promote the development of the disease." (PMID 36421826, 2022). "Thus, Gab2 mediates the inflammatory response in liver tissue and is involved in the development of hepatitis-induced liver cancer." (PMID 28842424, 2017).
liver cancer (2 papers, 2017 to 2022). An epithelial or non-epithelial malignant neoplasm that arises from the liver. "We screened for and identified two miRNAs targeting Gab2; these miRNAs inhibit the expression of the Gab2 gene and reduce cell proliferation and migration, providing new drug targets for the prevention and treatment of liver cancer." (PMID 36421826, 2022). "miRNA-663 has recently been found to target Gab2 to inhibit cell proliferation and invasion in liver cancer." (PMID 36421826, 2022). "First, we predicted Gab2-targeting miRNAs through biological websites, and we selected nine miRNAs that were reported in the literature as being abnormally expressed in liver cancer and fatty liver tissue." (PMID 36421826, 2022). "In conclusion, we identified two novel miRNAs targeting Gab2 and provided potential drug targets for the prevention and treatment of liver cancer." (PMID 36421826, 2022). "Our previous studies demonstrated that the signal integration protein Gab2 is a potential drug target for the prevention and therapy of liver cancer." (PMID 36421826, 2022). "Here, the ablation of Gab2 attenuated the inflammatory response in DEN-induced primary liver cancer in mice and decreased the production of inflammatory cytokines and the quantity of macrophages." (PMID 28842424, 2017). "Here, two miRNAs—miR-9 and miR-181a—were found to target Gab2 that inhibit the migration and proliferation of HepG2 cells, providing a novel potential method to prevent and treat liver diseases, including chronic diseases and cancers of the liver." (PMID 36421826, 2022). "Therefore, the study of miRNAs targeting Gab2 will be more effective in the identification of drug targets for the prevention and therapy of liver cancer." (PMID 36421826, 2022). "Deletion of Gab2 blocked DEN-induced primary liver cancer in mice." (PMID 28842424, 2017). "Furthermore, we detected the impact of Gab2 on liver cancer cell migration in a migration chamber assay." (PMID 28842424, 2017). "In addition, our previous study showed that Gab2 is expressed at a low level in normal liver tissue but expressed at abnormally high levels in alcoholic and non-alcoholic fatty liver and liver cancer, proving that Gab2 is a pathological factor related to liver disease." (PMID 36421826, 2022). "Therefore, Gab2 may be a very promising potential target for the prevention and treatment of liver cancer." (PMID 36421826, 2022). "Our results demonstrate that Gab2 is overexpressed in HCC and promotes the formation of liver cancer by integrating several signaling pathways, including the ERK, Akt, and Janus kinase (Jak) pathways." (PMID 28842424, 2017). "In addition, our previous study demonstrated that Gab2 could interact with PI3K, Socs3, and Shp2 in HepG2 cells upon treatment with ethanol or oleic acid, which were also the carcinogenic factors of liver cancer." (PMID 28842424, 2017). "Consistently, we also observed an increased expression of the Bcl-2, c-Myc, cyclinD1, and MMP7 target genes in primary liver cancer tissue from DEN-treated mice (red columns); however, the DEN-stimulated expression of these genes was significantly restrained by the absence of Gab2 (green columns)." (PMID 28842424, 2017).
liver disease (2 papers, 2021 to 2022). "These miRNAs would benefit from improving the prevention and treatment of liver diseases by inhibiting the expression of Gab2." (PMID 36421826, 2022). "A signal scaffold protein, Gab2, was demonstrated to be a potential preventive and therapeutic target for liver diseases in recent studies." (PMID 36421826, 2022). "Therefore, based on our research, we screened for and discovered two new Gab2-targeting miRNAs—miR-181a and miR-9—which are anticipated to improve the prevention and treatment of liver disease as potential biomarkers and therapeutic targets." (PMID 36421826, 2022). "However, deletion of the Gab2 gene or inhibition of the expression of the Gab2 protein expression ameliorates and prevents the pathology of liver disease pathology." (PMID 36421826, 2022). "Therefore, based on its ability to alter multiple pathological signals, Gab2 may be an effective target for the treatment of liver diseases." (PMID 36421826, 2022).
lymph node metastases (2 papers, 2017 to 2021). "Corroboration is obtained for GAB2 when suppression of the same reduces lymph node metastases and invasive cancer." (PMID 34764329, 2021). "In addition to poor tumor differentiation, lymph node metastasis, resection margin, and advanced TNM stage, univariate survival analyses revealed that the expression of GAB2, CRKL, FRS2 and the co-expression of GAB2/CRKL/FRS2 were also indicators for poor clinical outcome." (PMID 28558797, 2017).
myeloproliferative disease (2 papers, 2019 to 2022). "This would explain the protective effect of Gab2 deficiency in our model and highlights Gab2 (and its effectors) as a disease-specific vulnerability in myeloproliferative disorders." (PMID 34903841, 2022). "Y177 also recruits the scaffolding adaptor Gab2 via a Grb2/Gab2 complex for effective induction of the myeloproliferative disease." (PMID 31759365, 2019).
neuroblastoma (2 papers, 2020 to 2022). Neuroblastoma (NB) is the most common solid, extracranial childhood tumor. "Others have also reported that high-risk neuroblastoma associated with MYCN amplification cooperates with Gab2, a scaffold protein that amplifies EGFR signaling." (PMID 32260356, 2020). "It was reported that GAB2 plays important roles in neuroblastoma pathogenesis through promoting the cooperation of SHP2/MYCN." (PMID 35197367, 2022).
Rectal prolapse (2 papers, 2019 to 2021). Protrusion of the rectal mucous membrane through the anus. "In spontaneous disease, intestinal intraepithelial CD8+ but much fewer CD4+, T-cells from Gab2/3−/− mice with rectal prolapse were more proliferative." (PMID 30936879, 2019). "After LPS treatment, secreted protein levels of both TNFα and IFN-γ were significantly higher in BMDM conditioned media obtained from cells derived from Gab2/3−/− mice with rectal prolapse compared with WT." (PMID 30936879, 2019). "As early as 8 weeks of age, rectal prolapse was observed in Gab2/3−/− mice and approximately 1/3 of the mice developed rectal prolapse (50/136) compared to none detected in control mice as determined during a representative 15-month observation period." (PMID 30936879, 2019). "A comparison of WT, Gab2−/−, Gab3−/−, and Gab2/3−/− mice showed that maximal Lcn-2 increase was observed in double knockout mice (average of 26-fold), whereas mice with rectal prolapse had high Lcn-2 levels, but high Lcn-2 levels did not predict rectal prolapse." (PMID 30936879, 2019).
renal clear cell carcinoma (2 papers, 2024). "Meanwhile, GAB2 phosphorylation of T353 was also higher in the tumor in renal clear cell carcinoma." (PMID 38995439, 2024).
sarcoma (2 papers, 2019 to 2023). A usually aggressive malignant neoplasm of the soft tissue or bone. "Using these circuits, most sarcoma subtypes upregulate the intermediate proteins Lyn kinase, GAB2, or Vav proteins, which have dual roles in cancer progression." (PMID 37834179, 2023).
acute promyelocytic leukemia (1 paper, 2025). An aggressive form of acute myeloid leukemia (AML), characterized by arrest of leukocyte differentiation at the promyelocyte stage, due to a specific chromosomal translocation t(15;17) in myeloid cells. "GAB2 is likewise overexpressed in many human AMLs with mutations in NPM1 and/or signaling genes, and also in acute promyelocytic leukemia initiated by PML::RARA; the PML::RARA fusion protein may activate GAB2 by directly binding to its 5′ flanking region." (PMID 40773291, 2025). "We noted that human acute promyelocytic leukemia (APL) samples, a subtype of AML initiated by the PML::RARA fusion gene, had markedly higher expression of GAB2 than most other AMLs." (PMID 40773291, 2025).
basophilic leukemia (1 paper, 2009). "Gab2 also interacts with PLCγ2 in FcεRI-stimulated RBL-2H3 basophilic leukemia cells and RANKL-stimulated primary osteoclasts." (PMID 19737390, 2009). "Another study has demonstrated that Gab2 is subject to ubiquitin-mediated degradation in FcεRI-stimulated RBL-2H3 basophilic leukaemia cells." (PMID 19737390, 2009). "Similarly, knockdown of Gab2 expression with siRNA or antisense oligonucleotides in RBL-2H3 rat basophilic leukaemia cells, a widely used model system for mast cells, results in drastically impaired degranulation and cytokine production." (PMID 19737390, 2009).
cervical cancer (1 paper, 2021). A primary or metastatic malignant neoplasm involving the cervix. "In brief, we combined the Kaplan‐Meier plotter pan‐cancer database (including miRpower18 and mRNA) with clinical CESC patient sample data to demonstrate that the PAR2‐miR‐125b‐Gab2 pattern serves as a predictive model for prognostic risk in cervical cancer." (PMID 33369107, 2021).
cognitive decline (1 paper, 2021). "Genotyping of selected single-nucleotide polymorphisms in the APOE, ABCA7, SORL1, BIN1, GAB2, and CD33 genes was conducted, and a Bayesian hierarchical model was fitted to analyze the trajectories of cognitive decline among different genotypes." (PMID 34214049, 2021).
colon cancer (1 paper, 2024). "GAB2 phosphorylation of T353 shows higher expression in normal tissue in colon cancer." (PMID 38995439, 2024).
deafness (1 paper, 2020). An inherited or acquired condition characterized by the complete loss of the ability to hear from one or both ears. "For example, a dominant variant of METTL13 (DFNM1) completely suppresses recessive non-syndromic deafness DFNB26, associated with a variant of GAB2 with both genes functioning in the HGF/MET signaling pathway." (PMID 32987832, 2020).
emphysema (1 paper, 2017). "In a previous study, the expression of GAB2 in sputum was significantly increased in patients with severe emphysema compared to those who had minimal emphysema." (PMID 28438154, 2017).
esophageal cancer (1 paper, 2023). A primary or metastatic malignant neoplasm involving the esophagus. "It is reported that the increased of Gab2 promotes the migration and invasion of esophageal cancer cells through SHP2/ERK pathway." (PMID 37085900, 2023).
Fabry disease (1 paper, 2021). Fabry disease (FD) is a progressive, inherited, multisystemic lysosomal storage disease characterized by specific neurological, cutaneous, renal, cardiovascular, cochleo-vestibular and cerebrovascular manifestations. "Fabry's disease can be caused by the loss of lysosomal hydrolase α-galactosidase, which results in an increase in the Gab2 content." (PMID 34567412, 2021).
hyperthyroidism (1 paper, 2025). Overactivity of the thyroid gland resulting in overproduction of thyroid hormone and increased metabolic rate. "Results did not support the presence of interaction with these two conditions at any locus after multiple testing control, despite nominally significant P-values observed for SNP interaction with hyperthyroidism at SHROOM3 (P = 0.03) and with hypothyroidism at PIP5K1B (P = 0.03) and GAB2 (P = 0.04)." (PMID 40554574, 2025).
lung adenocarcinoma (1 paper, 2024). A carcinoma that arises from the lung and is characterized by the presence of malignant glandular epithelial cells. "GAB2 phosphorylation of S330, S505, and T353 shows higher expression in normal tissue in Lung adenocarcinoma." (PMID 38995439, 2024).
myelodysplastic syndrome (1 paper, 2022). A clonal hematopoietic disorder characterized by dysplasia and ineffective hematopoiesis in one or more of the hematopoietic cell lines. "The co-amplification of GAB2 in 70% of AML/myelodysplastic syndrome patients with MLL amplification provided the first hint for a role of GAB2 in AML." (PMID 34903841, 2022).
non- Hodgkin B-cell lymphoma (1 paper, 2022). "Its conjoined expression with GAB2 is a risk factor of non- Hodgkin B-cell lymphoma." (PMID 35265521, 2022).
osteosarcoma (1 paper, 2019). A usually aggressive malignant bone-forming mesenchymal neoplasm, predominantly affecting adolescents and young adults. "In osteosarcoma cells, miR-302a inhibits cell migration and invasion by directly targeting IGF-1R, and miR-302a can target GAB2, CXCR4, SDF1, Cyclin A, and Cyclin D to suppress cell proliferation, migration and invasion in glioma." (PMID 30765768, 2019).
ovarian adenocarcinoma (1 paper, 2017). An adenocarcinoma that arises from the ovary. "In addition, Gab2 mRNA and protein expression is notably up-regulated in ovarian serous cystadenocarcinoma—a subtype of ovarian adenocarcinoma with poor survival—compared with normal ovarian tissue." (PMID 28842424, 2017).
ovarian tumor (1 paper, 2016). "To investigate the role of GAB2 overexpression in tumorigenesis, we examined the effect of suppressing GAB2 by inducible RNA interference on ovarian tumor growth." (PMID 26657155, 2016). "Therefore, amplification and overexpression of GAB2 may represent one of the early genetic events that promote ovarian tumor growth, and as a result, ovarian tumors overexpressing GAB2 exhibit dependence on high GAB2 levels for tumor growth." (PMID 26657155, 2016).
pancreatic ductal adenocarcinoma (1 paper, 2017). An infiltrating adenocarcinoma that arises from the epithelial cells of the pancreas. "The purpose of the present study was to explore the expression and prognostic value of three adaptor proteins: GRB2-associated binding protein 2 (GAB2), CRK-like protein (CRKL) and fibroblast growth factor receptor substrate 2 (FRS2) in pancreatic ductal adenocarcinoma (PDAC)." (PMID 28558797, 2017). "Two earlier studies reported that GAB2 and CRKL were overexpressed in pancreatic ductal adenocarcinoma (PDAC), but they did not investigate the association of GAB2 and CRKL overexpression with the prognosis of PDAC patients." (PMID 28558797, 2017).
pulmonary fibrosis (1 paper, 2021). Chronic progressive interstitial lung disorder characterized by the replacement of the lung tissue by connective tissue, leading to progressive dyspnea, respiratory failure, or right heart failure. "Moreover, deficiency of either Gab1 or Gab2 can meliorate BLM-induced pulmonary fibrosis by destroying M2 macrophage polarization." (PMID 33637697, 2021).
renal carcinoma (1 paper, 2021). A carcinoma arising from the epithelium of the renal parenchyma or the renal pelvis. "Most of the genes have usually been investigated as prognostic biomarkers in renal cancer, and RPS18, RPL30, NME2, and RPS25 usually have been investigated as unfavorable predictors, while GAB2 has been reported as favorable predictor in renal cancer." (PMID 34208938, 2021).
Senile plaques (1 paper, 2013). Senile plaques are extracellular deposits of amyloid in the gray matter of the brain. "On the other hand the NFT (r = 0.20, p = 0.0009) and senile plaque counts (r = 0.19, p = 0.001) were higher in female brains thus indicating that sex maybe a contributing factor to the association of increased NFT and senile plaque counts with decreased cortical GAB2 levels." (PMID 23724096, 2013).